VHL (von Hippel-Lindau tumor suppressor)
Diseases named in the same sentence as VHL in open-access papers (continued):
Sharing a sentence is not in itself a finding about the gene and the disease.
tumor (continued). "However, some tumours without evidence of VHL inactivation also had elevated miR-210 and CAIX levels, indicating the likely operation of other mechanisms of HIF activation." (PMID 20964835, 2010). "Apart from its pro-apoptotic, growth inhibitory, and anti-angiogenic properties, this could be, at least in part, due to downregulating tumour progression and invasion-related genes (u-PAR, HIF1α, and VEGFC) and upregulating NSCLC tumour-related suppressor genes (FHIT, RASSF1, and VHL) by Enz." (PMID 20736951, 2010). "A small group of tumours (n=7, 6.9%) expressed pVHL and did not present any VHL alteration." (PMID 19755989, 2009). "A larger number of tumours with no VHL alteration would be needed to validate further our hypotheses through prospective clinical trials, and non-VHL molecular pathways that are involved in CCRCC should be better characterised." (PMID 19755989, 2009). "However, when separating tumours with no VHL alteration and tumours with at least one VHL hit, we were able to identify two groups non comparable in frequency but with very distinctive clinicopathological features and outcome." (PMID 19755989, 2009). "Moreover, none of the VHL patients (n>108) with PNET disease evaluated at our center had a functional neoplasm by hormone levels or symptoms." (PMID 19340311, 2009). "Although in this study we focused on the effect of VHL inactivation on CXCL12/CXCR4-mediated organ-specific metastases, it is possible that other hypoxia-inducible genes under the control of HIF-1α/VHL pathway may also play a role in tumor metastasis." (PMID 17083723, 2006). "Another tumor (case 2) had LOH at the RET and VHL gene locus but no somatic VHL mutation." (PMID 16707008, 2006). "Importantly, the VHL/HIF-1α signaling axis emerges as a critical regulatory target, which not only mediates glycolytic suppression but may also serve as a therapeutic strategy to curb tumor metastasis." (PMID 41008845, 2025). "Thus, PHD1-dependent Beclin1 hydroxylation and VHL-suppressed autophagy is not tumor-type-specific." (PMID 38360997, 2024). "Notably, BCL-XL and VHL were both highly expressed in tumor cells, but not in platelets." (PMID 39141428, 2024). "However, the immune infiltrations in the tumor microenvironment of VHL mutant ccRCC were not clear." (PMID 35624190, 2022). "The absence of tumour development in people with Chuvash polycythaemia suggests that deregulation of HIFα may not be sufficient to drive tumorigenesis in the VHL cancer syndrome and that VHL has other substrates that are required for tumour suppression." (PMID 35760869, 2022). "In addition, VHL inactivation leads to constitutive activation of hypoxia-inducing factor (HIF) HIF-1 and HIF-2 and their downstream targets (including pro-angiogenic factors VEGF and PDGF), while the activation of HIF and its downstream targets induces tumor formation." (PMID 33912215, 2021). "Individuals who subsequently developed a VHL-related tumour might have had a false negative genetic test or be phenocopies with respect to VHL disease through recurrence of the original haemangioblastoma or had a coincidental occurrence of another VHL-type tumour." (PMID 34573396, 2021). "In summary, considering the proposed VHL-dependent SARCC/AR/HIF-2α/c-MYC axis, VHL-wildtype RCC may experience a proliferation reduction under hypoxic conditions because of SARCC upregulation, whereas SARCC downregulation under hypoxia in VHL mutant RCC could lead to enhanced tumor proliferation." (PMID 32640630, 2020). "Consequently, VHL-deficient cancer cells failed to phosphorylate CARD9, resulting in constitutive activation of CARD9, an upstream trigger for NF-κB activation to induce tumor occurrence." (PMID 29352133, 2018).
tumor (continued). "To study the interactions among RNASEH2A, CDK1, and CD151 and their impact on tumor proliferation, we performed si-RNA knockdown studies on three ccRCC cell lines (786O, A704, KMRC3, all with VHL mutation) and one kidney urothelial carcinoma cell line (BFTC909, without VHL mutation)." (PMID 29843367, 2018). "However, VHL inactivation alone may not be sufficient to drive tumor formation as evidenced in genetically engineered Vhl−/− animal models." (PMID 29559707, 2018). "Specifically, in the complete absence of VHL the cells become spheroid and grow equally in all directions without any signs of differentiation whereas in the presence of VHL, tumor cells form aggregates that exhibit some traits of epithelial differentiation and may even form monolayers." (PMID 28187001, 2017). "However, a recent study showed Notch regulates tumor cell in hypoxia independent of VHL." (PMID 27612417, 2016). "However, SQAP could not inhibit tumor growth, tumor angiogenesis and reduce tumor hypoxia in VHL knockdown HAK1-B cells." (PMID 27119112, 2015). "In addition, utilization of this technology allowed for quantification of allelic frequency, revealing the cell non-autonomous role of VHL-inactivated hemangioblasts/stromal cells driving and sustaining the tumor cell mass via recruitment of intermixed normal endothelial cells." (PMID 25589003, 2014). "Secondly, heterozygous deletion of the mouse homologue of the VHL gene, Vhl (previously referred to as Vhlh), in the entire mouse, or homozygous deletion under the control of kidney-specific Cre transgenes, does not lead to proliferative dysregulation or tumour formation in the kidney." (PMID 23606570, 2013). "However, surveys have not been performed to reveal the specific nature of tumor cell processes and signaling networks that accompany the transformation to the VHL-mutant, HIF2α over-expressing (VHL-mut) RCC, particularly in relation to the VHL wild-type RCC lacking HIF2α (VHL-wt)." (PMID 23940778, 2013). "To identify the VHL-induced genes that could participate in the tumor-suppressing activity of VHL, we performed mRNA microarray experiments in which we compared gene expression in human RCC 786-O VHL(−) cells and the same cells with reconstituted, wild-type VHL (786-O VHL(+))." (PMID 23922894, 2013). "Interestingly, none of the VHL RNA from of these tumours showed an increase in the Δ2 isoform." (PMID 22825683, 2012). "A similar anticorrelation was observed comparing sporadic to SDHB tumours (Pearson’s ρ = −0.3515, p = 2.7 × 10–14) but not between VHL and SDHB tumours (Pearson’s ρ = −0.1409, p = 0.32)." (PMID 38124114, 2023). "To carry out such a multilevel investigation, we measured the mRNA levels of VHL, SETD2, PBRM1 and BAP1 genes by qPCR on the same tumour-normal paired sample set used for our CNV characterisation." (PMID 35586183, 2022). "The tumor genomic signature, i.e., lack of LOH, absence of somatic alterations in the VHL genomic regions, and absence of copy-neutral LOH, was consistent with the absence of the VHL phenotype in these patients." (PMID 35774415, 2022). "Tumor growth inhibition was dependent upon SMARCA2 degradation and was not due to non-specific effects of the chemical scaffold, as VHL and SMARCA2/4 -binding defective analogs A857 and A858 were not efficacious." (PMID 36357397, 2022). "This is further demonstrated in RCC tumor tissue where BNIP3 and VHL expression levels are lower compared to adjacent non-tumor tissues, whereas the expression of HIF-1α was higher in the same tumor tissues." (PMID 33573362, 2021).
tumor (continued). "However, extensive mutational analysis of tumor genes could not identify predictive markers of regorafenib efficacy, including among genes involving in angiogenesis (FLT1, FLT2, FLT3, FLT4, KDR, TEK (TIE2), and VHL)." (PMID 33322802, 2020). "Because platelets express minimal levels of VHL, DT2216 can potently degrade Bcl-xL in various tumor cells but not in platelets, in a VHL- and proteasome-dependent manner." (PMID 32677976, 2020). "In VHL-negative xenograft models, treatment with the VEGFR-selective inhibitor axitinib reduces tumor growth and prolongs survival, whereas treatment with crizotinib, which inhibits MET but not VEGFR, is much less effective." (PMID 28247252, 2017). "Without VHL, constitutively active transcription factor HIF is strongly oncogenic and is essential for tumor growth." (PMID 24260413, 2013). "Since VHL-PHEOs/PGLs have a better prognosis than SDHB-PHEOs/PGLs, the difference in HK2 does not seem to contribute to their distinct tumor aggressiveness in these particular tumors." (PMID 22859959, 2012). "Our results show that the SHH signaling pathway promotes tumor cell growth in human CRCC, regardless of the VHL status." (PMID 20015350, 2009). "In 2013, the laboratory of J. T. Hines designed a PROTAC based on the VHL peptide ligand and demonstrated for the first time that a PROTAC preferentially inhibited ovarian cancer cell proliferation and tumor growth in a mouse model without significant adverse effects on animal health." (PMID 36770884, 2023). "In mouse VHL–/– ccRCC xenograft experiments, silencing HIF2α using shRNAs or CRISPR/Cas9 suppresses tumor growth whereas forced production of HIF2α, such as through the expression of a non-hydroxylatable HIF2α mutant, bypasses pVHL’s tumor suppressor activity." (PMID 36106637, 2022). "Interestingly, none of VHL, SETD2, PBRM1 and BAP1 is indicated in these marker gene lists suspecting a missing link between the well-known DNA tumour markers and the actual behaviour of tumour cells." (PMID 35586183, 2022). "The only patient in the cohort with loss of PBRM1 (poly bromo-1) expression showed a distinct profile: a highly histopathological aggressive tumor with a marked angiogenic profile (VEGF overexpression and immature vascular stroma type 2), no PD1 or PDL1 expression, and WT status of the VHL gene." (PMID 32582758, 2020). "An increasing amount of evidence indicates the existence of HIF-independent pathways in the VHL-supervised background, as the simple inhibition of the HIF system might not be sufficient to prevent tumor progression." (PMID 33142830, 2020). "However, HIF-2α, but not HIF-1α, can overcome VHL's tumor suppressor activity and eliminating HIF-2α is sufficient to suppress tumor formation." (PMID 29560117, 2018). "For other known tumour suppressor loci, CDKN2C and FANCD2/VHL, our model could not identify this signature." (PMID 29089486, 2017). "However, for PHEOs/PGLs pseudo-hypoxia is not an indicator of tumor aggressiveness: SDHB- and VHL-derived PHEOs/PGLs share a pseudo-hypoxic phenotype, while exhibiting quite distinct risks for the development of metastases." (PMID 22859959, 2012). "While there was no obvious tumor inhibition treated by PCFC-g-PEI:VHL and HPEI:VHL complexes." (PMID 21513541, 2011). "Consistently, when selecting tumours with no detectable pVHL and at least one VHL alteration, it appeared that this latter group exhibited decreased VEGF tumour expression (P=0.0001) and VEGF plasma levels (P=0.002) compared with tumours expressing pVHL." (PMID 19755989, 2009).
tumor (continued). "A caveat is that some VHL–/– ccRCC lines are not affected by manipulations of HIF2 activity, suggesting they either were never HIF2-dependent or became HIF2-independent in the course of tumor progression in vivo or during cell line creation and passage ex vivo." (PMID 36106637, 2022). "Loss of poly bromo-1 expression showed a distinct profile: a highly histopathological aggressive tumor with a marked angiogenic profile (vascular endothelial growth factor overexpression and immature vascular stroma type 2), no PD1 or PDL1 expression, and wild-type (WT) status of the VHL gene." (PMID 32582758, 2020). "However, in other cancers where VHL inactivation is not prevalent, VEGF-driven angiogenesis may be just one of several tumour vascularisation pathways that the cancer can evolve to utilise." (PMID 24482243, 2014). "By performing siRNA experiments in a wild-type VHL background, we determined that invasion of the RCC cells was dependent on MT1-MMP rather than on the dysregulation of other VHL targets, suggesting that MT1-MMP may be responsible for RCC tumor invasion in the stromal compartment." (PMID 17140440, 2006). "Since, in our study, neither allelic imbalance of RET nor somatic VHL gene alterations occurred in the CCH specimen (presumably the precursor lesion of MTC), we suggest that such somatic VHL gene alterations rather play a role in tumor progression than in tumor formation of MEN2-related MTC." (PMID 16707008, 2006).
cancer (606 papers, 2002 to 2026). A tumor composed of atypical neoplastic, often pleomorphic cells that invade other tissues. "Cancer-associated Akt mutations result in loss of VHL/Akt interaction, thereby allowing cancer cells to proliferate even under hypoxic settings." (PMID 39851497, 2025). "By examining the DepMAP data, we found that nearly all human cancer cells cultured under 2D normoxia cannot tolerate the loss of VHL, while cells tended to gain growth benefit by HIF1A knockout under normoxic oxygen conditions." (PMID 38853928, 2025). "Patient 1, a 40-year-old female and her 20-year-old daughter (Patient 2) presented to our clinic after testing positive for a pathogenic variant in VHL (c.562C>G, p.L188V via Multi-Cancer Panel, Invitae Genetics)." (PMID 40063608, 2025). "The HIF‐2α inhibitor has recently been approved by the Food and Drug Administration for treating VHL‐mutated cancers, with potential future applications in advanced ccRCC." (PMID 40432277, 2025). "Somatic mutations generate a “second hit” that leads to cancer in the long run or changes to the epigenome that render the second copy of VHL inactive." (PMID 40362206, 2025). "Patient 4, a 37-year-old female, presented to our clinic after testing positive for a VHL pathogenic variant (c.562C>G, p.L188V via Multi-Cancer Panel, Invitae Genetics)." (PMID 40063608, 2025). "Background and Objectives: Von Hippel–Lindau (VHL) disease is caused by mutations in the VHL gene and can develop various cancers." (PMID 40005423, 2025). "In conclusion, this case-series highlights a growing phenomenon in cancer genetic counseling and testing: identification of incidental VHL variants." (PMID 40063608, 2025). "Overall, our VHL-deficient simulations indicate that a combination of VHL loss and cell cycle-promoting oncogene activation is required for cancer progression, breaking Hif-1⍺ and/or EMT-induced cell cycle arrest." (PMID 40238833, 2025). "Our model predicts that VHL loss alone, known to predispose patients to cancer, can push cells at moderate density and/or on a softer ECM into full EMT." (PMID 40238833, 2025). "Numerous studies have shown that VHL is an E3 ligase that mediates HIF-1α protein ubiquitination, and the reduction of its degradation, in turn, is caused by the VHL deficiency promoting cancer progression." (PMID 39920992, 2025). "Another three MGPs paired with VHL, a cancer driver gene frequently mutated in RCC, support the inhibition of indoleamine 2,3-dioxygenase 1 (IDO1) as a drug target, which was previously attempted." (PMID 38468344, 2024). "Across all cancers, low-scoring variants were predominantly found in tumors previously associated with VHL mutations." (PMID 38969834, 2024). "The tumors that show expression of hypoxia biomarkers have poor prognosis except for patients with human papilloma virus-associated or VHL-associated cancers." (PMID 38200568, 2024). "With the caveat that we cannot identify individual cells that are on a certain trajectory to cancer, detailed analysis of marked Vhl-null cells revealed multiple effects of potential relevance to VHL-associated oncogenesis." (PMID 38502859, 2024). "These ANGPTL4-low cancers are characterized by the increased frequency of wild-type Von Hippel-Lindau(WT VHL), a gene that is commonly mutated in ccRCC, and an enrichment for genes associated with lipid metabolism." (PMID 39105498, 2024). "We observed more than 100 cancer somatic mutations affecting the binding affinity of complexes formed by key RCC drivers such as VHL and TCEB1." (PMID 37964489, 2024). "Analysis of the distance of a missense mutation to the various interfaces in the VHL protein complex showed a tendency of cancer-causing mutations to be located in closer proximity to any of the protein interfaces within the VHL complex, P-value = 1.80E−3." (PMID 37883464, 2024). "Mutations in the Von Hippel–Lindau tumor suppressor (VHL) gene in humans have been associated with multiple types of cancer." (PMID 38320757, 2024).